IRS2 (insulin receptor substrate 2)
Diseases named in the same sentence as IRS2 in open-access papers (continued):
Sharing a sentence is not in itself a finding about the gene and the disease.
cancer (81 papers, 2008 to 2026). A tumor composed of atypical neoplastic, often pleomorphic cells that invade other tissues. "Pathway enrichment analysis uncovered significant alterations in pathways associated with adhesion, angiogenesis, and cancer-related processes, primarily characterized by a decrease in genes linked to aggressiveness in SW403sh-IRS2 cells." (PMID 39888380, 2025). "Insulin receptor substrates 1 and 2 (IRS1 and IRS2) play pivotal roles in insulin signaling, acting as intermediaries that transmit insulin’s effects to cellular processes closely associated with cancer." (PMID 38272982, 2024). "IRS1 plays a central role in cancer cell proliferation, in contrast, IRS2 is associated with cancer cell motility and metastasis." (PMID 24497996, 2014). "IRS2, encoding a kind of insulin receptor substrate that is commonly phosphorylated by the receptor tyrosine kinase, was reported to promote cell proliferation, invasion and sphere formation of cancer cells." (PMID 36092919, 2022). "Meta-analysis for the association between IRS2 rs1805097 Polymorphism and Cancer Risk." (PMID 24497996, 2014). "However, large-sample studies of different ethnic groups with well matched cases and controls are necessary to further clarify the role of IRS2 rs1805097 polymorphisms and these two types of cancer susceptibility in the future." (PMID 24497996, 2014). "Based on the information above, we propose that HIC1 potentially controls the proliferation and invasion of cancer cells by regulating AR expression and subsequently modulating the IRS2/PI3K/AKT pathway." (PMID 41050263, 2025). "To determine if BRD4 and IRS2 inhibitors can modulate the BMMCs immunosuppressive cancer microenvironment into an immunocompetent one, we measured the expression of several key tumor‐related immune molecules at the transcriptional and translational levels." (PMID 40285526, 2025). "Our research findings indicate that C-CBL mediated neddylation acts as an antagonist against insulin-associated cancer cell migration involving IRS1 and IRS2 in diverse cancer types." (PMID 38272982, 2024). "Knockdown of either IRS1 or IRS2 significantly reduced the migration effect induced by MLN4924 across all three cancer cell lines." (PMID 38272982, 2024). "Altogether, these findings suggest that neddylation genuinely participates in IRS1 and IRS2-dependent insulin signaling, effectively suppressing cancer cell migration." (PMID 38272982, 2024). "We then validated the endogenous interaction between NEDD8 and IRS1 as well as IRS2 in all three cancer cell lines, affirming the neddylation E3 ligase function of C-CBL." (PMID 38272982, 2024). "To investigate this, we first validated the endogenous expression levels of IRS1 and IRS2 in all three types of cancer cell lines by using C-CBL targeting si-RNA (si-C-CBL) under prolonged insulin treatment." (PMID 38272982, 2024). "The resources developed in this study should be of value in studying the complexity of IRS2 function and dynamic regulation, as well as the potential of IRS2 as a therapeutic target in cancer." (PMID 39305958, 2024). "Our study aims to explore the molecular function of IRS1 and IRS2 in relation to neddylation and its effect on cancer cell migration." (PMID 38272982, 2024). "The R24C mutation prevents INK4-family CDK4 inhibition; in cancers, Cdk4-R24C mutation is synergistic with loss of function of Cip/Kip inhibitors, suggesting that Cdk4-R24C may counteract a damaging combination of loss of cyclin D2 with gain of p27 in IRS2 null β cells." (PMID 37712417, 2023). "Further studies are necessary to clarify the roles of IR-A and IRS2 in metastatic processes and cancer cell progression." (PMID 36975518, 2023). "IRS-2 is generally related to processes such as metastasis, migration, and cell invasion in different types of cancer, while IRS-1 is related to proliferation." (PMID 36975518, 2023).
cancer (continued). "In the group in which CR was obtained, the presence of cancer disappeared on the image, and the AUC of IRS2 was relatively low." (PMID 37568686, 2023). "The results of pan-cancer analysis in this study describe the expression levels of four genes (Irs2, Plin2, Pnpla2 and Srebf2) in various types of cancerous tissues compared to normal tissues." (PMID 37047411, 2023). "IRS1- and IRS2-induced signaling is highly modulated during many cancer processes, such as cell motility, metastasis, and cell proliferation." (PMID 36975518, 2023). "Several genes located in 13q34 have been associated with a worse prognosis in other cancers, including CUL4A and TFDP1, IRS2 and CDC16." (PMID 35887382, 2022). "The crosstalk of progesterone and PR with IGF-1 signaling via IRS2 promote growth of breast and cervical cancer cells." (PMID 35816477, 2022). "It is reported that IRS1 plays a key role in cancer cell proliferation and mediates the resistance to anticancer drugs, while IRS2 acts mainly in cancer cell motility and metastasis." (PMID 34093789, 2021). "Among all IRSs, IRS-1 and IRS-2 are ubiquitously expressed with high expression in various cancer cell lines." (PMID 33991522, 2021). "IRS-1 is responsible for tumor proliferation, whereas IRS-2 promotes cancer cell motility and invasion." (PMID 33991522, 2021). "Among the top 5% of DEGs most significantly changed, we found Prtg, Lin28, Greb1, and Irs2, known as positive regulators of cell proliferation upregulated in cancer." (PMID 32985705, 2020). "Intriguingly, some of the possible miR-141 targets are associated with cancer metastasis e.g. DLC1, insulin receptor substrate 2 (IRS2) and salt-inducible kinase 1 (SIK1)." (PMID 28095864, 2017). "Nedd4 and Epsin1, which coordinately enhance IGF-I-induced IRS-2 tyrosine phosphorylation, are often overexpressed in cancer cells." (PMID 26074875, 2015). "Insulin receptor substrate-2 (IRS-2), a signaling adaptor protein, was involved in two cancer-related pathways (the phosphatidylinositol 3′-kinase (PI3K) and the extracellular signal-regulated kinase (ERK) pathways)." (PMID 24497996, 2014). "Owing to its presence in these important cancer-related pathways, IRS-2 was considered to be one of factors accelerating tumor progression and metastasis." (PMID 24497996, 2014). "Several growth factor/hormone signaling pathways that are associated with cancer including fibroblast growth factor (FGF), epidermal growth factor (EGF) and insulin can modulate IRS-1 and IRS-2 expression levels." (PMID 19534786, 2009). "Indeed, published work indicates that the inhibition of BRD4, GAB2, or IRS2 restrains the progression of several types of cancer." (PMID 40285526, 2025). "Hence, these findings highlight the critical role of IRS1 and IRS2 neddylation in facilitating cancer cell migration under conditions of insulin signaling dysfunction." (PMID 38272982, 2024). "It has been shown that the A isoform of the insulin receptor (IR-A) is often overexpressed, and its stimulation induces changes in the expression of the insulin receptor substrates (IRS-1 and IRS-2), which are expressed differently in the different types of cancer." (PMID 36975518, 2023). "A recent study using next-generation sequencing technology to test cancer-related genes has shown that several targeted mutations (KRAS, PIK3CA, IRS2, Sox2, and HRR genes) may potentially become effective targeted treatment sites for patients." (PMID 35909972, 2022). "In addition, insulin receptor substrate 2 (IRS2), which is elevated in insulin signaling pathways through let-7a, has recently gained wide attention in cancer development and progression." (PMID 36140796, 2022). "Taken together, the presence of IRS2, a candidate driver oncogene, may modulate metabolic activities and response to therapy in cancer patients, particularly in those with high BMI." (PMID 35816477, 2022). "IRS‐2 has been shown to undergo nuclear translocation in normal and cancer cells." (PMID 34485840, 2021).
cancer (continued). "In summary, we demonstrate that PDK-1 knockdown induced cancer cell apoptosis may be through Hippo–YAP/IRS2 signal pathway." (PMID 30988063, 2019). "Ingeneral, IRS1 suppresses, while IRS2 induces the migration of cancer cells." (PMID 30807634, 2019). "Overexpression IRS2 mitigated PDK-1 silence induced cancer cell apoptosis." (PMID 30988063, 2019). "AIB1 has been implicated in several cancers, and attenuation of AIB1 frequently inhibits the activation of Akt signaling by suppressing the expression of insulin receptor substrate (IRS)-1 and IRS-2." (PMID 27486509, 2016). "Abnormal expression of ATF3 may mediate multiple aspects of cancer biology by repressing the transcription of certain downstream molecules including Cyclin D1, Id1 and IRS2." (PMID 25149542, 2014). "Additionally, we found that the levels of IRS-2, a central modulator of insulin signalling in normal and cancer cells and a target of microRNA33a as well were modulated by metformin." (PMID 24980829, 2014). "Moreover, the dimer downregulates the expression of Bromodomain‐containing protein 4 (BRD4), GRB2‐associated‐binding protein 2 (GAB2), and Insulin receptor substrate 2 (IRS2) proteins, all of which play crucial roles in cancer cell sustainability and progression." (PMID 40285526, 2025). "Our research underscores the significant role of Cbl proto-oncogene (C-CBL) as a neddylation E3 ligase for IRS1 and IRS2, highlighting the promising potential of C-CBL as a target for regulating cancer metastasis in the context of insulin dysregulation." (PMID 38272982, 2024). "Within our study, we observed that inhibiting neddylation enhances cancer cell migration across different cancer types by activating both insulin receptor substrates 1 and 2 (IRS1 and IRS2), along with the PI3K/AKT signaling pathway." (PMID 38272982, 2024). "In this paper, we collected data about the molecular mechanisms that explain the relevance of IRS4 in the development of cancer and identify IRS4 differences that distinguish it from IRS1 and IRS2." (PMID 37760618, 2023). "Let-7a target gene (WNT7A, β-catenin, IRS2, and FZD4) expression significantly increased in T2–T4 compared with pT1 as let-7a miRNA inhibition stimulates FZD4 and Wnt/β-catenin pathway in cancer cells." (PMID 36140796, 2022). "The IRS2, IGF2, and ATG12 proteins were present mainly in cancer metabolic pathways, including the MAPK, FOXO, and RAS signaling pathways." (PMID 34976838, 2021). "For IRS2, RRS1 and MRPL5, we observed that the fold change in expression is comparable in cancer and under BPA treatment, suggesting that BPA presence can bias the predictive power of these genes." (PMID 34062972, 2021). "It is likely that TRAF4 and Nedd4 differentially regulate IRS-1 and IRS-2 ubiquitination and subsequent IGF-1 signaling in cancer cells." (PMID 33991522, 2021). "In the present study, we observed that PDK-1 is highly expressed in NSCLC cell lines; PDK-1 depletion promoted cancer cell apoptosis and inhibited cell proliferation through Hippo–YAP/IRS2 signal pathway." (PMID 30988063, 2019). "In other cancer cells, many genes have been identified as miR-338-3p targets, including ADAM17, PREX2a, ZEB2, Sox4, SMO, MACC1, and IRS2." (PMID 29618948, 2018). "The purpose of this article is to provide the data on all TFBSs in the promoter region of human IRS-2 gene as it has the potential for prediction of the regulation of IRS-2 gene in normal or diseased cells from patients with metabolic disorders and cancer." (PMID 26858982, 2016). "Taken together, many studies indicate that IRS-1 and IRS-2 play redundant roles in cancer development, but some reports clearly show their distinct roles: IRS-1 tends to promote cancer proliferation whereas IRS-2 preferentially promotes cell migration." (PMID 26074875, 2015). "We then collected 27 cell lines, including four cancer cell lines with the highest mRNA expression levels, and checked for the expression of IRS1, IRS2 and IRS4 proteins by Western blotting." (PMID 24039912, 2013).
cancer (continued). "However, IRS1 and IRS2 may have divergent functions in cancer metastasis." (PMID 23112878, 2012). "Many of the motifs are conserved between the two family members, and IRS-1 and IRS-2 have been reported to activate common signaling pathways including PI3K and the Erk1/2 MAPK kinases in a variety of cancer model systems." (PMID 19534786, 2009). "In conclusion, this study demonstrated for the first time that IRS-2 could modulate protein secretion, which markedly expands our understanding of the role of IRS-2 in IGF signal pathway activation and cancer cell proliferation." (PMID 37894751, 2023). "Three of these genes (RELN, IRS2, and FOXP1) have a known association with non-CRC digestive cancers and one (RRAS2) has a known association with non-CRC cancer." (PMID 37627102, 2023). "Additionally, the expression levels of IRS2 in cancer tissue from the 34 LUAD patients were significantly higher than that in paired paraneoplastic tissue, supporting the idea that IRS2 promote proliferation in LUAD." (PMID 35844799, 2022). "The protein subnetwork of PIK3R2 could be used for further pan-cancer studies in the future: DUSP10, DUSP6, FHL2, IRS2, PIK3R2, and RIPK2." (PMID 36329531, 2022). "Not surprisingly, similarity among different cancer types was identified in only 6 out of 23 clusters, including E3 (IRS2, KRT6A), E5 (CD24, STMN1), E8 (GKN1, MUC5AC), E9 (PHGR1, TFF3), E10 (TFF3, TPO) and E13 (VTN and ITIH5)." (PMID 36333338, 2022). "Extensive molecular profiling revealed that a number of components of the IGF signaling pathway, including insulin receptor substrate-2 (IRS2) and IGF-binding protein-5 (IGFBP5) among others, play key roles in determining the sensitivity of cancer cells to a humanized IGF1R antibody." (PMID 32391121, 2020). "One of these genes was insulin receptor substrate 2 (IRS2), which has previously been identified as a low-frequency amplified gene in GBM and is described as a putative driver oncogene in several other cancers." (PMID 32669109, 2020). "Hence, it seems likely that subversion of Irs2-dependent aspects of the LPC response identified in our study also contribute to the pathophysiology of metabolic liver disease and cancer." (PMID 30695023, 2019). "Extensive molecular profiling revealed that a number of components of the IGF pathway, including IRS2 and IGFBP5, may play key roles in determining the sensitivity of cancer cells to humanized IGF1R antibody figitumumab." (PMID 28706506, 2017). "In addition, depletion of IRS-2 significantly diminished tumor growth and metastasis in various organs of mice, thus indicating that IRS-1/2 can serve as a positive regulator of cancer progression." (PMID 37894751, 2023). "However, the roles of adaptor proteins IRS1 and IRS2 have not been investigated in this type of cancer." (PMID 36975518, 2023). "IRS2 is an insulin-like growth factor-1 receptor (IGF-1R) and insulin receptor signaling transmitter, which may be involved in the PI3K-AKT pathway, leading to the occurrence and progression of malignant tumors and inhibition of apoptosis." (PMID 36277284, 2022). "Small molecule TGF‐β enhancers, which potentiate TGF‐β growth inhibition by enhancing TβR‐I–TβR‐II‐mediated canonical signaling and thus activating TβR‐V‐mediated tumor suppressor signaling cascade (TβR‐V/IRS‐2/PP1/pRb), could be used to prevent and treat carcinoma." (PMID 34485840, 2021). "In oncology, IRS1 and IRS2 knockout mice as well as IRS1- and IRS2-overexpressing murine models were used to elucidate the function of these proteins in solid tumors, providing evidence of distinct and nonredundant functions for both proteins in cancer development and progression 106, -108." (PMID 30328953, 2018).
tumor (75 papers, 2009 to 2026). "In vitro knockdown of ALDH1A3 or associated genes such as FAM3C, MCC, PMEPA1, and IRS2 reduced tumor invasion, while in vivo reduction similarly curbed tumor growth and metastasis." (PMID 40781158, 2025). "Pathway analysis revealed notable alterations linked to IRS2 overexpression in pathways associated with tumor aggressiveness, including extracellular matrix remodeling, cell adhesion, and locomotion." (PMID 39888380, 2025). "In 786-O primary tumor cell line we observed decrease expression of genes of insulin-associated proteins (IRS2, CBL), transcription regulators (AEBP1), PI3 kinase signaling (AKT1, BCL2L1) as well as lipid metabolism genes (ACOX1)." (PMID 30929166, 2019). "A significant inverse association between IRS-2 cytoplasmic staining intensity and tumor grade was observed when IRS-2 expression was dichotomized to low versus high expression (p = 0.009)." (PMID 31393907, 2019). "The positive association of IRS-2 with poor outcomes in ADC likely reflects its role in regulating tumor cell functions that promote tumor progression." (PMID 31393907, 2019). "Generally, IRS1 is associated with tumor initiating programs such as growth and survival while IRS2 is associated more closely with progression and metastasis." (PMID 27765041, 2016). "Although IRS-1 is most often related to tumor growth and proliferation, IRS-2 is most frequently associated with tumor motility and invasion." (PMID 26029165, 2015). "Two in-frame insertion mutations in IRS-2, one germline (p.Ala701_Val702insAla) and the other tumor-associated (p.Asn28_His29insAsn), were identified in CRC cases." (PMID 23877285, 2013). "Although IRS2 has been positively associated with aggressive tumor behavior, it has also been identified as a primary target gene of AR." (PMID 22844442, 2012). "Similar to IRS-1, IRS-2 has also been implicated in promoting tumor cell survival, which is likely to contribute to its role in tumor progression." (PMID 19534786, 2009). "A general theme arises from these studies; IRS-1 and IRS-4 are most often associated with tumor growth and proliferation and IRS-2 is most often associated with tumor motility and invasion." (PMID 19534786, 2009). "Our studies demonstrate that acute degradation of IRS2 recapitulates the reduction of tumor cell invasion that we previously observed upon chronic IRS2 loss, validating further investigation of how targeting IRS2 may impact tumor progression." (PMID 39305958, 2024). "This new mutation might selectively change the function of IRS2 to promote tumor invasion, resulting in axillary lymph node metastasis presenting first." (PMID 38750402, 2024). "IRS1 loss and IRS2 accumulation may represent important mechanism underlying AFB1-induced tumor progression." (PMID 23112878, 2012). "IRS1 deficient tumor cells are more invasive, while IRS2 deficient tumor cells are less invasive." (PMID 23112878, 2012). "These in vitro findings support the hypothesis that Irs-2 compensates for the loss of Irs-1, and in doing so, enhances the activation of signaling pathways that promote tumor metastasis." (PMID 19534786, 2009). "In response to mitotic stress, cells that lack IRS2 or express a PLK1-binding deficient mutant exhibit reduced centrosome separation and a shortened mitotic arrest that leads to reduced tumor cell viability." (PMID 41951610, 2026). "Increased IRS2 expression was noted in BM compared to LM (P < 0.0001) and primary tumor samples (P = 0.0004)." (PMID 39888380, 2025). "To further investigate the impact of HIC1/AR/IRS2 on the proliferation and metastasis of PCa cells, we conducted immunohistochemical analysis on PCa xenograft tumor slices." (PMID 41050263, 2025). "Analysis of the DFN cells in vivo will also allow for the investigation of IRS2 expression and localization at the cellular and whole tumor levels." (PMID 39305958, 2024).